ATM (ATM serine/threonine kinase)
Diseases named in the same sentence as ATM in open-access papers (continued):
Sharing a sentence is not in itself a finding about the gene and the disease.
prostate carcinoma (continued). "NKX3.1, one of the prostate cancer suppressor, can interact with ATM leading to activate ATM, enhance the DDR and thus contribute to DNA integrity in prostate epithelial cells." (PMID 32459662, 2020). "The National Comprehensive Cancer Network prostate cancer guideline recommends genetic counseling for patients with prostate cancer and having BRCA1/2, ATM, PALB2, or FANCA mutation." (PMID 31931827, 2020). "The application of PARP inhibitors in the treatment of prostate cancer was initiated in 2015 following the finding that 19.6% of prostate cancers had BRCA1, BRCA2 or ATM mutations." (PMID 33015058, 2020). "Emerging data has also linked several germline DNA mutations to prostate cancer, namely BRCA1, BRCA2, MSH, ATM, PALB2, CHEK2, and MUTYH." (PMID 32957584, 2020). "BRCA2 and ATM mutated, as well as ETS-fusion-positive prostate cancers have the highest percentage of gains, while the majority of CDK12-mutant tumors do not have any change in ploidy." (PMID 31366128, 2019). "Of these, BRCA2, BRCA1, and ATM account for 19.3% overall and they were substantially more frequent in mCRPC compared to those in primary prostate cancers." (PMID 31357527, 2019). "Prostate cancer patients who have mutations in the DNA repair pathway (such as BRCA1, BRCA2, ATM, RAD51D and PALB2) have been shown to be significantly more likely to have advanced disease than patients without these mutations." (PMID 31915536, 2019). "In prostatic cancer, miR-421 was also found to inhibit ATM expression and promote prostate cancer metastasis and treatment resistance." (PMID 31857500, 2019). "Although N-Myc differentially regulates miR-421/ATM pathway in different stages of prostate cancer, the biological consequence of both regulations is to facilitate the progression of NEPC from PCA and the development of therapeutic resistance." (PMID 30657058, 2019). "Immunoblotting was used to quantify expression of pS1981 ATM in irradiated (2 Gy) human prostate cancer LNCaP cells exposed to solvent control or ENZ." (PMID 30933998, 2019). "Surprisingly, N-Myc overexpression upregulated ATM expression in C4–2 cells and this upregulation promoted migration and invasion of prostate cancer cells." (PMID 30657058, 2019). "In contrast, it has been shown that upregulation of ATM leads to radioresistance in castrate‐resistant prostate cancer, allowing cells to repair radiation‐induced DNA damage." (PMID 29845714, 2018). "This is the first study to demonstrate that 10 μM DT increased the S phase proportion of the cell cycle and phosphorylated ATM and γH2AX expression in prostate cancer cells." (PMID 29386061, 2018). "Extending the use of PARP inhibitors, beyond tumors with defective BRCA1/2, ATM, CHEK2, Fanconi's Anemia genes is of great interest, expecially in prostate cancer, where mutations in DNA repair genes are rare." (PMID 28415632, 2017). "Excluding skin cancer, only the BRCA2/ATM pathogenic variant carrier reported multiple primary cancers (MBC and prostate cancer)." (PMID 28008555, 2017). "We demonstrate how fungal GL induces DDR via ATM/ATR-CHK1 pathway, causing apoptosis and G2/M cell cycle arrest in prostate cancer, inhibiting tumor growth in vivo in mouse tumor models." (PMID 26683224, 2016).
prostate carcinoma (continued). "LOX-PP also inhibits radiation-induced activating phosphorylation of ataxia-telangiectasia mutated (ATM) and checkpoint kinase 2 (CHK2) to inhibit DNA repair pathways in prostate cancer xenograft growth." (PMID 28036074, 2016). "Down-regulation of ATM protein also sensitizes human prostate cancer cells resulting in an increase in radiation induced apoptosis." (PMID 22096476, 2011). "In prostate cancer, the activity of ATM is compromised, and repair activities are carried out by DNA-PK." (PMID 29147215, 2010). "Compared with wild-type (WT) tumors, significantly more adaptive immune response cells, especially tumor-infiltrating lymphocytes (TILs), are enriched in BRCA1/2 mutant TNBC, as well as prostate cancer and pancreatic cancer with BRCA2, PALB2, or ATM germline mutations." (PMID 40830526, 2025). "Although olaparib has been used as a targeted therapy for ATM‐mutated ovarian and prostate cancers, its application in treating ATM‐mutated NSCLC has not been established." (PMID 40622001, 2025). "At the gene level, our case-control collapsing analysis confirms associations between rare damaging variants in four genes and increased prostate cancer risk: SAMHD1, BRCA2 and ATM at the study-wide significance level (P < 1×10−8), and CHEK2 at the suggestive threshold (P < 2.6×10−6)." (PMID 39971927, 2025). "Early prostate cancer is largely characterized by the accumulation of single nucleotide variants (SNVs) in genes like forkhead box protein A1 (FOXA1) and ATM, along with deletion of tumor suppressor genes like NKX3-1 and retinoblastoma transcriptional corepressor 1 (RB1)." (PMID 40863429, 2025). "There was consensus that prostate cancer screening advice for males with a GPV in ATM or CHEK2 should be given at the time of diagnosis, including advice to seek a reassessment if there were any further cancer diagnoses in the family or if they have specific questions about their genetic diagnosis." (PMID 41159931, 2025). "We, therefore, hypothesized that ATM would be an effective targeting strategy for increasing the efficacy of Ra-223 therapy for the treatment of prostate cancer bone metastases." (PMID 40978127, 2025). "Furthermore, mutations in DNA damage repair genes such as BRCA2, ATM, CHEK2, BRCA1, RAD51, and PALB2 have been implicated in familial prostate cancer." (PMID 40716035, 2025). "In our observations, two male patients were treated for a prostate cancer diagnosed at an early age, which might suggest that the BRCA2-linked risk is further increased by the presence of the ATM PV." (PMID 38929805, 2024). "Previously, it was shown that the natural compound, resveratrol, which inhibits complex I of the ETC, sensitized radioresistant prostate cancer cells by increasing ATM phosphorylation and its target protein γ-H2AX, resulting in cell cycle arrest and subsequently cell death." (PMID 39404412, 2024). "Similarly, for PARP inhibitors, much of the focus in prostate cancer has been on the “synthetic lethality” mechanism, which has resulted in these agents becoming available for the treatment of patients with BRCA1/2 or ATM-loss prostate cancer." (PMID 38672592, 2024). "Furthermore, a study in prostate cancer demonstrated that upon exposure to doxorubicin E2F1 was recruited to the promoter region of ATM and repressed its expression." (PMID 38519707, 2024). "For example, the HRD scores of patients with prostate cancer were significantly lower than those of patients with ovarian cancer, and the HRD scores of patients with prostate cancer and BRCA2 mutations were significantly higher than those of patients with ATM and CHEK2 mutations." (PMID 36791952, 2023).
prostate carcinoma (continued). "Germline pathogenic variants (PVs) in the Ataxia Telangiectasia mutated (ATM) gene (MIM* 607585) increase the risk for breast, pancreatic, gastric, and prostatic cancer and, to a reduced extent, ovarian and colon cancer and melanoma, with moderate penetrance and variable expressivity." (PMID 37509701, 2023). "We examined the aggregate association of rare germline pathogenic/likely pathogenic/deleterious (P/LP/D) variants in ATM, BRCA2, PALB2, and NBN with a polygenic risk score (PRS) on prostate cancer risk among 1,796 prostate cancer cases (222 metastatic) and 1,424 controls of African ancestry." (PMID 38014910, 2023). "Other genes associated with tumorigenesis of prostate cancer, such as ATM, MKI67, and SPOP, showed non-significant increases in somatic mutation frequency in the low-TICS group." (PMID 36918939, 2023). "ATM and PALB2 have limited data for prostate cancer risk but may be important when considering precision treatment, such as PARP inhibitors in the metastatic setting." (PMID 37240284, 2023). "Importantly, ATM-mediated phosphorylation of Sam68 in prostate cancer cells modulates alternative polyadenylation of transcripts that are targets of Sam68, supporting the notion that the ATM–Sam68 axis exerts a multifaceted role in the response to DNA damage." (PMID 36010841, 2022). "Indeed, results from a large pan-cancer WGS study include ATM among the top 26 driver genes in these cancers, being found altered in 9 and 7% of pancreatic cancer and prostate cancer samples, respectively." (PMID 35563100, 2022). "Mutations found in ATM and CHEK2 genes were associated with aggressive prostate cancer." (PMID 35892882, 2022). "In addition, five prostate cancer–associated genes (EGF, PIK3R1, ATM, BRCA1, and BRCA2) with apparent damaging mutations, one of which is a rare mutation in ATM, a possible therapeutic target, further support this claim." (PMID 36643868, 2022). "Apparently, those with BRCA2 mutations respond better to PARP inhibitors as compared to the prostate cancer patients with ATM and CHEK2 alterations; nevertheless, the same correlation with higher genomic scarring composite scores has been revealed in the respective DDR gene mutations." (PMID 36010882, 2022). "PROREPAIR-B is an ongoing prospective study to evaluate the outcomes of patients with metastatic castrate-resistant prostate cancer with and without germline ATM/BRCA1/BRCA2/PALB2 mutations." (PMID 35732815, 2022). "Beyond acting as a potential prognostic biomarker for prostate cancer, ATM status may also be predictive of response to novel targeted therapies." (PMID 35008949, 2022). "ATM mutations and high-risk prostate cancer have been associated in some studies through screening of patients with advanced disease, although BRCA2 remains the only gene in which pathogenic variants have been consistently linked to aggressive prostate cancer." (PMID 35892882, 2022).
prostate carcinoma (continued). "On the other hand, the first major biomarker study in prostate cancer (PCa) (the PROfound study) reported that 17.6% of the 4425 patients had mutations in at least one of the predefined 15 HRR genes, which included BRCA1, BRCA2, and ATM." (PMID 35055413, 2022). "In addition to breast cancer and ovarian cancer, there are also several clinical trials on PARP inhibitors for BRCA1/2- or ATM- mutant patients with prostate cancer or cervical cancer [NCT04641728]." (PMID 35055413, 2022). "For example, prostate cancer patients with BRCA1- mutations could be selected for clinical trials and for treatments with olaparib and ATM inhibitor, provided that the drug combination is approved by the FDA." (PMID 35055413, 2022). "Genetics of prostate cancer have shown population specific features, particularly related mutations in HOXB13, NBN, and CHEK2; however mutations in BRCA2, mismatch repair genes, BRCA1, and ATM appear to contribute to risk in many populations." (PMID 34503195, 2021). "Rare variants in several genes that were initially implicated in risk for breast or ovarian cancer predisposition (e.g., BRCA1, BRCA2, CHEK2, BRIP1, and ATM), as well as the mismatch repair (MMR) genes, have also been reported to increase the risk of prostate cancer." (PMID 33804961, 2021). "Moreover, in the ATM, BRCA1 and BRCA2 genes from prostate cancer patients, the distributions of germline benign, pathogenic, VUS, and recurrent somatic variants differ across Pfam domains." (PMID 34253785, 2021). "Our study applied a new recommended definition of aggressive prostate cancer and provides further evidence that rare germline pathogenic variants in ATM, BRCA1, and BRCA2 are associated with increased risk of this aggressive, clinically relevant subset of prostate cancer." (PMID 33804961, 2021). "Germline mutations of BRCA1/2 and ATM are associated with worse prognosis in prostate cancer, while to-date, somatic mutations are not shown to be." (PMID 33781305, 2021). "A recent study evaluating plasma cfDNA from 69 patients with advanced prostate cancer found that up to 10% of patients can have CHIP involving HRR genes (primarily ATM but also BRCA2 and CHEK2), suggesting a need for paired whole‐blood samples as a control to avoid misdiagnosis." (PMID 33630412, 2021). "Indeed, prostate cancer cells promote ATM expression via recruitment of the androgen receptor to the ATM gene enhancer region." (PMID 34070860, 2021). "This suggests that PARP inhibitors could be expanded to other indications, including BRCA-mutated prostate cancer and those harbouring mutations in DDR proteins such as ataxia-telangiectasia mutated (ATM)." (PMID 32444694, 2020). "Targeting CDC6 together with Chk1/2 inhibitor could suppress TopBP1-ATR-Chk1 signaling and increase phosphorylation of ATM, a biomarker of DNA damage, synergistically increasing the treatment efficacy in prostate cancer cells." (PMID 32792963, 2020). "A larger cross-sectional analysis of 1328 men with prostate cancer by Giri and colleagues found 15.6% carriers of germline mutations; 10.9% patients carried a mutation in DNA repair genes (BRCA2 > CHEK2 > ATM > BRCA1), increasing the risk of more advanced tumors (Gleason score ≥ 8)." (PMID 33322746, 2020). "Moreover, aberrations of BRCA2, BRCA1, and ATM were observed in mCRPC at clearly higher frequencies than in primary prostate cancers." (PMID 31366128, 2019). "It prompted us to see whether N-Myc overexpression overcomes the ADIS by modulating miR-421/ATM pathway in prostate cancer cells." (PMID 30657058, 2019).
prostate carcinoma (continued). "For instance, PARP inhibitors olaparib and rucaparib have been approved to treat BRCA-defective ovarian or prostate cancer patients while GC patients harboring low-ATM gains greater survival benefit than high-ATM patients when treated with olaparib plus paclitaxel." (PMID 29954437, 2018). "Our findings identify miR‐106a and LITAF as novel modulators of radioresistance through ATM upregulation and suggest that miR‐106a may be a promising biomarker for high‐grade disease and radioresistant prostate cancer." (PMID 29845714, 2018). "Notably, 19 ATM truncations were also detected in other cancer types, mostly in lung, stomach and prostate cancers, the respective fractions of cases being 1.1% (5 out of 462 cases), 1.2% (4 out of 321 cases) and 3.4% (6 out of 178 cases)." (PMID 26689913, 2015). "The fact that androgen treatment alone can induce TMPRSS2: ERG fusion in the prostate cancer, LNCaP, cell line suggests that these cells may contain a detective ATM/ATR DNA damage checkpoint." (PMID 23272087, 2012). "The ATM/ATR DNA damage checkpoint functions in the maintenance of genetic stability and some missense variants of the ATM gene have been shown to confer a moderate increased risk of prostate cancer." (PMID 23272087, 2012). "Finally, at the gene-level, we tested for genetic association between aggressive prostate cancer and controls, and found that PTVs in BRCA2 (OR = 8.23 [6.17–10.85], P = 1.47 × 10−36) and ATM (OR = 5.27 [3.65–7.46], P = 1.74 × 10−16) were significantly associated with aggressive disease." (PMID 39971927, 2025). "For example, loss‐of‐function (LOF) variants and variants of unknown significance (VUS) in the ataxia‐telangiectasia‐mutated (ATM) gene were reported to be enriched in cases with MPM, and the most common nonmelanoma cancers among these patients were BCC followed by prostate cancer." (PMID 35932099, 2022). "The Advanced Prostate Cancer Consensus Conference held in 2019 supported consideration of BRCA1 and BRCA2 testing in screening, management, and informing prognosis/treatment, with germline testing recommended in patients with a tumour BRCA1, BRCA2, or ATM mutation." (PMID 33630412, 2021). "Moreover, ATR inactivation has been proposed to be synthetic lethal with ATM inactivation because of the overlapping substrates and functions of ATR and ATM, and because ATM appears inactivated in a significant proportion of cancers (10–16% of colorectal, gastric, lung and prostate cancers)." (PMID 34572827, 2021). "By combining data from 13 research studies, representing 5560 men with prostate cancer and 3353 unaffected controls, the PRACTICAL consortium conducted the largest gene sequencing study of ATM and estimated an OR for overall prostate cancer risk of 4.4 (2.0–9.5) for pathogenic ATM variant carriers." (PMID 33804961, 2021). "A study using prostate cancer cell lines agreed that ATM loss may not respond to PARPis, but they did respond well to an ATR inhibitor." (PMID 33233320, 2020). "Interestingly, this study provided also evidence that prostate cancer patients with aberrations in Fanconi anemia-complex genes or in ATM serine/threonine kinase displayed markedly longer treatment responses to carboplatin than did patients without defects in genes encoding DNA repair proteins." (PMID 31366128, 2019). "Furthermore, the Human Protein Atlas revealed that ATM is overexpressed in prostate cancer." (PMID 29845714, 2018).